PPARG (peroxisome proliferator activated receptor gamma)
Diseases named in the same sentence as PPARG in open-access papers (continued):
Sharing a sentence is not in itself a finding about the gene and the disease.
ischemia (continued). "In the present study, we hypothesized that peroxisome proliferator-activated receptor-gamma (PPARγ)-dependent pathway can reduce the expression of p-Drp1(Ser616) and ameliorate hippocampal injury induced by global ischemia in rats." (PMID 27175924, 2016). "By targeting the PPARγ pathway with PPARγ agonists that potentially lead to induction of M2 microglia, several groups have shown efficacy in treating traumatic brain injury and ischemia." (PMID 24889886, 2014). "PPARγ agonists can inhibit the phosphorylation of JAK1/2 and STAT1/3 in the reperfusion zone of ischemia-reperfusion (IR)-injured rats, decrease their neurological score, and reduce the IR injury in brain tissue." (PMID 33281727, 2020). "In contrast, none of five PPARγ-/F:MORE+/Cre neonates examined in the current report showed ischemia, hemorrhage or necrosis of small or large bowel suggesting that the original observation was not related solely to PPARγ deficiency." (PMID 27505464, 2016). "We first reported that PEDF inhibits vascular permeability in RAECs via PPARγ under the hypoxic condition and found that PEDF protected cardiomyocytes against ischemia or hypoxia-induced cell apoptosis, both in vivo and in vitro via preventing the activation of caspase-3." (PMID 25768344, 2015). "Application of the synthetic PPARγ ligand pioglitazone or the natural PPARγ agonist 15-deoxy-Δ12,14-prostaglandin J2 (15d-PGJ2) before ischemia could attenuate lung I/R injury in rats." (PMID 22481914, 2012). "However, the involvement of HIF-1α in the amorfrutin B-evoked decrease in PPARγ expression during ischemia cannot be excluded as amorfrutin B does not affect this factor during ischemia." (PMID 34440058, 2021). "There is some evidence suggesting that this PPARγ activation following blockade of the AT1 receptor could be part of its anti-inflammatory and antioxidative effects, leading to neuroprotection against ischemia and Aβ accumulation." (PMID 23320146, 2012). "The relationship among endothelial over-expression of sEH (Tie2-sEH Tr), the changes in oxylipins it may produce, the pharmacologic inhibition of ω-hydroxylases, activation of PPARγ, and CRH response to a brief ischemia is not known." (PMID 28056085, 2017).
multiple sclerosis (42 papers, 2007 to 2025). A progressive autoimmune disorder affecting the central nervous system resulting in demyelination. "A selective antagonist of PPARγ, bisphenol A diglycidyl ether, causes deteriorating clinical performance in a model of multiple sclerosis." (PMID 26028469, 2015). "In multiple sclerosis (MS), a PPARg polymorphism has been shown to be linked to the disease; in fact, the Ala/Ala genotype of the Pro12Ala PPARg polymorphism is associated with a delayed onset of disease." (PMID 25722716, 2015). "Moreover, multiple sclerosis patients are highly susceptible to PPARγ-mediated suppression of Th17 cell development, strongly asserting PPAR-γ as a promising target for specific immunointervention in autoimmune disorders." (PMID 27872515, 2016). "In studies on multiple sclerosis (MS), excessive activation of PPARγ can inhibit mitophagy and exacerbate the accumulation of ROS and oxidative stress." (PMID 41413911, 2025). "A PPARγ-mediated lenabasum response in pDCs has been shown in a multiple sclerosis model, where treatment with lenabasum resulted in a trending decrease in TNFα and IFNα, with or without CB2R inhibition." (PMID 40383862, 2025). "The same report shows that loss of PPARγ increases the severity of experimental autoimmune encephalomyelitis (EAE) and multiple sclerosis in mouse models, leading to a greater infiltration of Th17 cells into the central nervous system." (PMID 31922096, 2019). "PPARγ expression also seems to have relevance to multiple sclerosis (MS), with lower expression levels of PPARγ reported in PBMC from MS patients compared to healthy controls." (PMID 27548145, 2016). "In addition, in an experimental model of multiple sclerosis, PPARγ exerted an important role in mediating the effects of CBD." (PMID 33171772, 2020). "These two trials highlight the potential of PPARγ agonists for multiple sclerosis." (PMID 31614690, 2019). "Demyelination in multiple sclerosis (MS) cells is the site of several energy metabolic abnormalities driven by dysregulation between the opposed interplay of peroxisome proliferator-activated receptor γ (PPARγ) and WNT/β-catenin pathways." (PMID 29659554, 2018). "Other PPARγ antagonists are implicated in neurotoxicity, bisphenol A diglycidyl ether (BADGE) worsens clinical scores in the experimental allergic encephalomyelitis model of multiple sclerosis." (PMID 22417924, 2012). "While the effects of VCE-004.8 over multiple sclerosis pathogenesis are CB2R- and PPARγ-independent, BCP beneficial effects were reported to depend on CB2R activation at lower concentrations and PPARγ activation at higher concentrations." (PMID 33498245, 2021). "Only limited clinical evidence exists on the potential therapeutics of PPARγ agonists, pioglitazone and CHS-131 (also known as INT-131) for multiple sclerosis." (PMID 31614690, 2019). "For example, deletion of either PPARγ, PPARδ, or LXRα/β results in aggravated disease progression in experimental autoimmune encephalomyelitis (EAE), the animal model of Multiple Sclerosis." (PMID 28926619, 2017). "In conclusion, CBD, through both enhanced PPARγ and modulation of the PI3K/Akt/mTOR pathway, could be an interesting therapeutic target for multiple sclerosis." (PMID 33171772, 2020).
neuroblastoma (40 papers, 2006 to 2025). Neuroblastoma (NB) is the most common solid, extracranial childhood tumor. "Recent studies show that this hexapeptide is able to affect the peroxisome proliferator-activated receptor gamma (Pparγ) in mouse astrocytes and undifferentiated neuroblastoma cells (SH-SY5Y) in vitro." (PMID 38914873, 2025). "9-HODE is an agonist of PPARγ, which when activated stimulates axonal outgrowth in primary rat hippocampal neurons and human neuroblastoma cells." (PMID 36758902, 2023). "The choice of human neuroblastoma cells to be used as a neurodegeneration model for this application stems from the knowledge that PPARγ appears highly active as a transcription factor in SH-SY5Y cell line." (PMID 34728675, 2021). "MiR-27b represses the growth and progression in neuroblastoma cell by targeting Peroxisome Proliferator Activated Receptor Gamma (PPARγ)." (PMID 32782028, 2020). "miR-27b targets the 3’-untranslated region (3’-UTR) of PPARγ and inhibits its mRNA and protein expression in neuroblastoma cells." (PMID 28095798, 2017). "In neuroblastoma cells, PPARγ is a target of miR-27b as determined by 3’-UTR luciferase reporter and endogenous protein assays." (PMID 28095798, 2017). "PPARγ expression is also found to correlate with maturation stage of primary neuroblastoma tissue with differentiated phenotype having high nuclear PPARγ expression." (PMID 29018329, 2017). "This is the case in the SK-N-AS neuroblastoma cells and derived mouse xenografts, where miR-27b was shown to repress PPARγ expression resulting in a decreased inflammatory response and tumor growth." (PMID 28167956, 2017). "In the neuroblastoma cell line ND-7, the same group showed that the degree of PPARγ activation induced by PGJ2 is modulated through an interaction with the retinoblastoma protein (Rb) and histone deacetylase." (PMID 20339586, 2010). "The putative natural PPARγ agonist, 15d-PGJ2, inhibits cellular growth, decreases cellular viability and induces apoptosis in human neuroblastoma cells in vitro, although some effects have been demonstrated to be PPARγ-independent." (PMID 20339586, 2010). "In another publication, the same authors showed that the VGVAPG peptide influenced the expression of PPARγ mRNA also in the neuroblastoma cell line SH-SY5Y, although the role of PPARγ in the mechanism of action of the VGVAPG peptide in these cells has not yet been thoroughly investigated." (PMID 34374904, 2022). "In addition, the CYP2D6 gene is positively regulated by PPARγ, as shown in vitro in neuroblastoma SH-SY5Y cells and in vivo in the cerebellum and liver of mice." (PMID 36359909, 2022). "Moreover, the PPARγ agonists ciglitazone and pioglitazone promote neurite outgrowth in neuroblastoma cells." (PMID 33926552, 2021). "However, one study showed that miR-27b-3p targeted PPARG to inhibit tumor growth and progression in neuroblastoma cells." (PMID 32850439, 2020). "Similarly, synthetic PPARγ agonists have been shown to inhibit cell growth in several neuroblastoma cell lines." (PMID 29018329, 2017). "Thus, the sensitivity of different neuroblastoma cell lines to different PPARγ agonist varies owing to their cellular heterogeneity." (PMID 29018329, 2017). "It has been proposed that DEHP might impair fetal brain development through activation of Trim17 protein via PPARγ (peroxisome proliferator-activated receptor-γ) leading to apoptosis based on an in vitro study of neuroblastoma cells." (PMID 25280125, 2015). "PPARγ is present in neuroblastoma cell lines, as well as in primary neuroblastoma cell culture." (PMID 20339586, 2010). "Importantly, CBD also decreased APP expression in APP-transfected human neuroblastoma cells by inducing APP ubiquitination through peroxisome proliferator-activated receptor gamma (PPARγ), which was paralleled by a reduction of Aβ peptide expression and increased cell survival." (PMID 36117622, 2022).
neuroblastoma (continued). "In addition to its role in hepatocytes, adipocytes, and cardiomyocytes, the relevance of miR-27b targeting of PPARγ was also highlighted in several other tissues (inflammatory cells, renal tubular cells, and pulmonary endothelial cells as well as neuroblastoma)." (PMID 28167956, 2017). "In IMR-32 human neuroblastoma cells, however, LPA antagonizes 15-deoxy-Δ12,14-prostaglandin J2-mediated PPARγ activation." (PMID 23467751, 2013). "It has been reported that serum lysophosphatidic acid attenuates both the degree of PPARγ activation and the cellular response to 15d-PGJ2 in neuroblastoma cells." (PMID 18261208, 2008). "In this study, our aim is to determine a coactivator of PPARγ, PGC-1α, and to test whether this coactivator can protect neuroblastoma cells from Aβ-induced neurotoxicity." (PMID 28946859, 2017). "PPARγ is expressed in the central nervous system, and 15-deoxy-PGJ2, a natural PPARγ ligand stimulates differentiation of pheochromocytoma 12 (PC12) and human neuroblastoma cells." (PMID 23741474, 2013). "The results contribute to the current knowledge on neuroblastoma differentiation by showing that CDDO induced neurite outgrowth, decreased viability, up-regulation of differentiation markers and down-regulation of active CREB were PPARγ dependent events in IMR32 cells." (PMID 29018329, 2017).
liposarcoma (39 papers, 2002 to 2026). A usually painless malignant tumor that arises from adipose tissue. "The PPARγ agonist is known to induce differentiation of liposarcoma to adipose tissues, but a phase II trial of rosiglitazone against liposarcoma showed no clinical response." (PMID 40371227, 2025). "As PPARγ was overexpressed in liposarcoma cells, it is likely that the dedifferentiation in Ad/N1ICD adipocytes was derived from the deficient activation of PPARγ due to the suppression in the cells of lipid metabolism pathways that supply ligands to PPARy." (PMID 33917351, 2021). "Strikingly, Horvai and collaborators reported that the PPARγ protein can be detected in the vast majority of dedifferentiated liposarcomas, with specific nuclear staining in 93% of DDLPS tested." (PMID 32158531, 2020). "The markers of other sarcoma types, such as Ewing sarcoma marker, FLI‐1 38, chondrosarcoma or neurogenic sarcoma marker, S100 38, liposarcoma marker, PPARγ 39, and leiomyosarcoma marker h‐caldesmon 38, tested negative in tumors formed by SiRb‐OeMyc." (PMID 28191765, 2017). "Further analyses will help to understand the correlation between PPARγ expression and tumor malignancy in liposarcoma." (PMID 27401457, 2016). "Demetri and colleagues conducted a small clinical trial of the PPARγ agonist troglitazone (TGZ) in patients with liposarcoma." (PMID 22643847, 2012). "Tontonoz and colleagues were able to show that primary human liposarcoma (LPS) cells were effectively induced to undergo terminal adipocytic differentiation following treatment with the PPARγ agonist, pioglitazone." (PMID 22643847, 2012). "These promising preclinical results regarding the differentiative effects of PPARγ agonist treatment in liposarcoma have been subsequently pursued in a clinical phase II trial utilizing the PPARγ agonist rosiglitazone." (PMID 22643847, 2012). "Perhaps one of the more pronounced effects of PPARγ activation is seen with PPARγ agonist treatment of liposarcoma." (PMID 22643847, 2012). "Introduction of FUS-CHOP into mice, where expression of the transgene is driven by the ubiquitously expressed elongation factor 1α (EF1α) promoter, results specifically in liposarcomas with inherent induction of adipocyte specific genes such as PPARγ." (PMID 21253554, 2011). "As mesenchymal malignancies thatarise from adipose tissue, liposarcomas express PPARγ atlevels comparable to normal adipose tissue." (PMID 19125177, 2008). "Since adipose tissue has the highest expression of PPARγ, liposarcomas have a theoretical advantage using this treatment as compared to other tumours." (PMID 14562008, 2003). "Tontonoz and colleagues demonstrated that PPARγ agonists such as pioglitazone could induce terminal differentiation in liposarcoma cells, transforming malignant cells into mature adipocytes." (PMID 41614813, 2025). "PPARγ is under the repressive control of the FUS-CHOP fusion oncogene in mixoid liposarcoma." (PMID 36119484, 2022). "Reduced PPARG mRNA levels in high grade liposarcoma tissues supports the possibility that, in DDLPS, terminal differentiation is blocked at the early steps of mesenchymal cell commitment to adipogenesis that initiate PPARG2 expression rather than post-PPARG2 induction." (PMID 35313831, 2022). "Taken together, these findings suggest that FUS-DDIT3 could prevent the development of committed adipocytic precursors in liposarcoma through the interference with PPARγ and C/EBPα expression, two transcription factors with a critical role in adipogenesis." (PMID 18596980, 2008). "PPARγ expression is a distinguishing featureof liposarcomas relative to other soft tissue sarcomas." (PMID 19125177, 2008). "The anticancer activity of PPARγ agonists was first demonstrated in a liposarcoma model." (PMID 15467764, 2004).
liposarcoma (continued). "Similarly, the impaired expression of PPARγ and C/EBPα in liposarcomas of CombitTA-FUS-DDIT3 mice was normalized following administration of tetracycline (4 gr/L in the drinking water for 2 weeks, a dose sufficient to suppress of exogenous -FUS-DDIT3 expression)." (PMID 18596980, 2008). "A significant elevation in PPARγ expression was reported in MLS, pleomorphic liposarcoma, and dedifferentiated liposarcoma, particularly in differentiated areas of dedifferentiated liposarcoma, compared with lipoma or well-differentiated liposarcoma." (PMID 27401457, 2016). "Additionally, the authors showed that PPARγ is highly expressed in the major histological types of liposarcoma, suggesting that PPARγ-targeting agents, especially combined with RXRα ligands, may be useful therapy for human liposarcoma." (PMID 22966225, 2012). "Although troglitazone was later withdrawn due to hepatotoxicity and rosiglitazone, another PPARγ agonist, was not effective as an anti-tumor drug in the treatment of liposarcoma." (PMID 41614813, 2025). "Given its prominent role in adipogenesis, it is not surprising that increased expression of Pparγ/Rxr has been found in liposarcomas that were triggered to undergo terminal differentiation in vitro by thiazolidinediones or TZDs (class of antidiabetic drugs) and Rxr-specific retinoids." (PMID 34195082, 2021). "In liposarcoma, two phase II trials with PPARγ agonists (either troglitazone or rosiglitazone) indicated cell differentiation of the solid tumors without, however, correlation between drug-induced PPARγ activity in the tumor and the clinical coutcome." (PMID 22654896, 2012). "Unfortunately, recentstudies reveal the tumor-promoting and pro-angiogenic PPARγ activities; while in most cases PPARγ agonists attenuate tumor growth and angiogenesis,troglitazone (TGZ, a now rejected PPARγ agonist) promotes hepaticcarcinogenesis and liposarcomas." (PMID 19043603, 2008). "Thus and with the aim of clarifying the relationship between the PPARγ and C/EBPα pathways in liposarcomas, we next assessed the role of the C/EBPα downregulation in the process of adipogenesis in FUS-DDIT3 MEFs, as these MEFs show a dramatic downregulation and inactivation of PPARγ." (PMID 18596980, 2008). "This implies that focusing on PPARγ as a specific antitumoral target is not likely to be successful, because PPARγ ligands are not an active agent for the treatment of metastatic CRC or liposarcoma." (PMID 20814432, 2010).